CAPN1 (calpain 1)
Diseases named in the same sentence as CAPN1 in open-access papers (continued):
Sharing a sentence is not in itself a finding about the gene and the disease.
colorectal cancer (2 papers, 2021 to 2023). A primary or metastatic malignant neoplasm that affects the colon or rectum. "An increased expression of calpain-1 was detected in colorectal cancer and correlated with poor overall survival (OS), advanced pathological grade, and metastasis." (PMID 33430230, 2021). "Calpain-1 deficient SW480 and HT29 cells (an in vitro model of colorectal cancer achieved by siRNA) exhibited significantly reduced of cell invasion and migration processes, which ultimately promoted tumour progression and metastasis compared to controlled cells." (PMID 33430230, 2021).
COVID-19 (2 papers, 2023 to 2024). A disease caused by infection with severe acute respiratory syndrome coronavirus 2. "Our study examined the association between serum calpain 1 activity and IL-33 concentration in patients with COVID-19 ARDS." (PMID 37509486, 2023). "Elevated values of calpain 1 activity in our study of COVID-19 patients with developed ARDS are consistent with earlier studies that indicate the role of calpain 1 in acute lung parenchymal damage." (PMID 37509486, 2023). "The role of calpain 1 in enhancing the inflammatory response, cell apoptosis, and fibroproliferative processes supports its increased levels in patients with COVID-19 ARDS, as demonstrated in our study." (PMID 37509486, 2023). "In addition, the role of calpain 1 has also been described in terms of the internalization of the virus into cells, and its inhibitors are placed in the context of potential drugs for the treatment of COVID-19." (PMID 37509486, 2023). "Our study showed increased calpain 1 activity and IL-33 concentration in the serum of COVID-19 patients who developed ARDS compared with those who did not, with a positive correlation between these two values." (PMID 37509486, 2023). "Our research showed elevated calpain 1 activity and IL-33 concentration in the serum of COVID-19 patients who developed ARDS compared to those who did not develop ARDS and a positive correlation between them was established." (PMID 37509486, 2023).
endothelial dysfunction (2 papers, 2021 to 2026). In vascular diseases, endothelial dysfunction is a systemic pathological state of the endothelium (the inner lining of blood vessels) and can be broadly defined as an imbalance between vasodilating and vasoconstricting substances produced by (or acting on) the endothelium. "Calpain-1 exists in endothelial cells and participates in the formation of endothelial dysfunction." (PMID 34840664, 2021).
epilepsy (2 papers, 2018 to 2022). A brain disorder characterized by episodes of abnormally increased neuronal discharge resulting in transient episodes of sensory or motor neurological dysfunction, or psychic dysfunction. "Interestingly, CAPN1 is well ranked (no deletion or duplication) in the ExAC CNV records and it is not covered by BCG, epilepsy and autism data sets used in this study." (PMID 30148849, 2018).
esophageal cancer (2 papers, 2025). A primary or metastatic malignant neoplasm involving the esophagus. "Another study has indicated that CAPN1/CAPN2 can facilitate cisplatin-induced pyroptosis in esophageal cancer." (PMID 40520022, 2025). "Additionally, in esophageal cancer treated by cisplatin, an identified mechanism of action involves the activation of calpain-1/2 (CAPN1/2)/Bcl-2 homologous antagonist/killer (BAK)/Bcl-2-associated X protein (BAX)/caspase-9/caspase-3/GSDME signaling axis." (PMID 41291696, 2025).
gastric cancer (2 papers, 2016 to 2021). A primary or metastatic malignant neoplasm involving the stomach. "In contrast to calpain-1 and calpain-2 isoforms, the downregulation of calpain-9 expression was associated with metastasis in patients with gastric cancer, suggesting the protective effect of calpain-9 expression and its roles in hampering gastric cancer progression." (PMID 33430230, 2021). "Because calpains were reported to function in the process of oncotic cell death, we further detected calpain-1 in QC4-treated gastric cancer cells by Western Blotting." (PMID 27057539, 2016). "QC4 inhibited cell proliferation dose- and time-dependently and destroyed cell membrane integrity, activated calpain-1 autolysis, and induced apoptotic protein cleavage in gastric cancer cells." (PMID 27057539, 2016).
idiopathic pulmonary fibrosis (2 papers, 2018 to 2023). Idiopathic pulmonary fibrosis (IPF) is a nonneoplastic pulmonary disease that is characterized by the formation of scar tissue within the lungs in the absence of any known cause. "Increased expression of calpain 1, combined with the reduced expression of E-cadherin in the lungs of patients with idiopathic pulmonary fibrosis, indicates a relationship between ubiquitous calpains and EMT in pulmonary fibrosis." (PMID 37626391, 2023). "Another study reported that intraperitoneal injections of bleomycin protected calpain-1/2 conditional knockout mice against lung fibrosis." (PMID 37626391, 2023). "In another study, intratracheal administration of bleomycin, the most common route of bleomycin-induced lung fibrosis, elevated the expression levels of calpain 1 and 2, which was subsequently suppressed by calpeptin." (PMID 37626391, 2023). "In a mouse model of bleomycin-induced pulmonary fibrosis, calpeptin downregulated calpain 1/2 mRNA expression in the lungs." (PMID 37626391, 2023). "Likewise, the protein levels of calpain-1, calpain-2 were increased, suggesting that BLM-induced calpain activation in lung fibrosis." (PMID 29666896, 2018).
lung carcinoma (2 papers, 2019 to 2022). "The Calpain family where CAPN1 belongs can influence the malignancy phenotype of lung cancer cells by degrading proteins according to some reports and also is involved in various cellular processes containing cell signal transduction and apoptosis, etc.." (PMID 36092153, 2022).
meningioma (2 papers, 2018). A generally slow growing tumor attached to the dura mater. "Increased expression of CAPN1 has been observed in schwannomas and meningiomas and heightened expression of CAPN2, in colorectal adenocarcinoms." (PMID 30131853, 2018). "Importantly, here we detect a similar 75 kDa calpain-1 form also in vivo, in human meningiomas." (PMID 29572388, 2018). "While we detected the 46 kDa fragment of calpain-1 in the crude lysates from meningiomas, the lower Mr species was produced only in vitro, where activation of calpain-1 proceeds in the absence of any other substrate, except for calpain-1 itself, and at a non-physiological [Ca2+]." (PMID 29572388, 2018).
mucinous carcinoma (2 papers, 2019). "Syk, MAP4 and calpain-1 appeared to significantly correlate with each other in the whole cohort, with calpain-1 being more highly associated with MAP4 and Syk in mucinous carcinomas." (PMID 30737623, 2019).
muscular dystrophy (2 papers, 2015 to 2021). Muscular dystrophy (MD) refers to a group of more than 30 genetic diseases characterized by progressive weakness and degeneration of the skeletal muscles that control movement. "The patient with CAPN1 and DYSF pathogenic variants did indeed have a severe muscle weakness attributed to the muscular dystrophy." (PMID 33486633, 2021). "Deficiency in a calpain can lead to disease: platelet dysfunction (calpain-1), muscular dystrophy (calpain-3), stress-induced gastric ulcer (calpains 8 and 9), and calpain-2 deficiency is embryonically lethal." (PMID 26527411, 2015).
Myokymia (2 papers, 2015 to 2023). Myokymia consists of involuntary, fine, continuous, undulating contractions that spread across the affected striated muscle. "Thus, three of the ataxic Jack Russell Terriers and the Danish-Swedish-Farm Dog with neuromyotonia, myokymia and facial rubbing were homozygous for the wild-type alleles at both CAPN1:c.344G>A and KCNJ10:c.627C>G." (PMID 25998802, 2015). "Delay and/or absence of central BAEP waves (described in detail in9, 26) were found in all dogs biallelic for the KCNJ10 variant, but not in the Parson Russell terrier biallelic for the CAPN1 variant, nor in a dog with myokymia/neuromyotonia alone." (PMID 37905444, 2023). "Although myokymia was not clinically, neuromyotonic discharges were recorded in the tongue muscle of the Parson Russell terrier biallelic for the CAPN1 variant." (PMID 37905444, 2023). "Neither myokymia nor neuromyotonia is reported in association with KCNJ10 or CAPN1 variants in humans or in experimental animal models." (PMID 37905444, 2023). "Information on the breed, clinical phenotype (spinocerebellar‐like ataxia and myokymia/neuromyotonia) and genotype (KCNJ10 and CAPN1) of the 33 investigated dogs." (PMID 37905444, 2023).
Obesity (2 papers, 2016 to 2017). Accumulation of substantial excess body fat. "Exclusion of all cases with a BMI higher than 30 (value widely considered as the limit of obesity) and below 19 (considered as underweight or even cachectic) results in increased correlation coefficients compared to the total group for cTnT dp2 and calpain 1 dp1." (PMID 26951243, 2016). "To investigate the role of calpains in diet-induced obesity, we used CAST overexpressing transgenic mice to inhibit activities of both calpain-1 and -2." (PMID 29089532, 2017).
osteosarcoma (2 papers, 2013 to 2025). A usually aggressive malignant bone-forming mesenchymal neoplasm, predominantly affecting adolescents and young adults. "In our study, the expression of calpain 1 and calpain 2 was first examined, and the results showed that calpain family proteins were clearly present in all osteosarcoma cell lines." (PMID 40959067, 2025). "A previous report showed that calpain 1 and calpain 2 were involved in the adhesive and invasive abilities of osteosarcoma cells by affecting MMP-2 secretion." (PMID 23855590, 2013). "However, calpain 1 and calpain 2 seem to play a more sophisticated role in osteosarcoma, which is shown with the opposite effects in 143B cell lines." (PMID 40959067, 2025).
Ovarian tumours (2 papers, 2012 to 2019). "Ovarian tumours of the serous type were associated with high expression of calpastatin (χ2 = 23.755, d.f. = 4, P < 0.001), high calpain-1 (χ2=15.961, d.f. = 4, P = 0.003) and high calpain-2 (χ2 = 26.02, d.f. = 4, P < 0.001)." (PMID 22435971, 2012). "Since stage reflects the extent of ovarian tumour spread in vivo, calpain-1 may be involved in tumour migration and invasion in vitro." (PMID 30448882, 2019).
psoriasis (2 papers, 2017 to 2024). An autoimmune condition characterized by red, well-delineated plaques with silvery scales that are usually on the extensor surfaces and scalp. "At last, PD 151746 (calpain-1 inhibitor) treatment decreased epidermal thickness in imquimod-induced psoriasis model." (PMID 28060905, 2017). "Then mS100a7a15 and calpain-1 positive cells in IMQ-induced psoriasis skin are higher than that in normal skin by immunohistochemistry." (PMID 28060905, 2017). "All the data mean that mature IL-1α, mS100a7a15 and calpain-1 are positive expressed in IMQ-induced psoriasis mouse model." (PMID 28060905, 2017). "Then, we proved mS100a7a15, mature IL-1α and calpain-1 were highly expressed in imquimod-induced psoriasis model and mouse IL-17a-neutralizing antibody treatment attenuated mS100a7a15 expression." (PMID 28060905, 2017). "Importantly, mature IL-1α and calpain-1 expression were decreased in the psoriasis-like lesions in the treatment of PD151746." (PMID 28060905, 2017). "Also, mS100a7a15, calpain-1 and mature IL-1α protein levels were induced in psoriasis-like skin compared to normal skin." (PMID 28060905, 2017). "Taken together, our results suggest that mature IL-1α induced by hS100A7 is via RAGE-p38 MAPK and calpain-1 pathway in keratinocyte and this mechanism may play an important role during psoriasis." (PMID 28060905, 2017). "Importantly, in a mouse model of psoriasis, calpain-1 inhibition improved epidermal hyperplasia, alleviated skin inflammation and reduced the expression levels of mature IL-1α and calpain-1." (PMID 28060905, 2017). "In psoriasis, for instance, S100A7 was found to induce the expression of mature interleukin-1α via the RAGE-p38 MAPK-calpain 1 pathway, which triggers an inflammatory response in the body." (PMID 38255845, 2024).
pulmonary arterial hypertension (2 papers, 2023 to 2024). Pulmonary arterial hypertension (PAH) is a group of diseases characterized by mean pulmonary artery pressure >20 mmHg and elevated pulmonary arterial resistance leading to right heart failure. "Previous studies in our laboratory have shown that Calpain-1 mediates vascular remodeling and fibrosis with hypoxia pulmonary hypertension through HIF-1α." (PMID 38878112, 2024). "In addition, studies using mouse models of hypoxia-induced pulmonary hypertension and pulmonary arterial smooth muscle cells suggest that calpain-1 may be important for hypoxia-inducible factor-1α-mediated vascular remodeling and fibrosis." (PMID 37626391, 2023). "According to previous research results in our laboratory, Calpain-1 mediates vascular remodeling and fibrosis through HIF-1α in hypoxia pulmonary arterial hypertension." (PMID 38878112, 2024).
retinal degeneration (2 papers, 2023 to 2024). Degeneration of the retina. "High Ca2+-levels likely suppress protective activity of calpain-1 and promote retinal degeneration via activation of calpain-2." (PMID 38303059, 2024). "In our study, treatment could not block rd1 retinal degeneration completely, suggesting that beneficial effects resulting from calpain-2 inhibition might have been offset by simultaneous calpain-1 inhibition." (PMID 37189329, 2023).
spinal muscular atrophy (2 papers, 2021 to 2024). A motor neuron disease that affect the muscles, and characterized by muscle weakness and atrophy resulting from progressive degeneration and irreversible loss of the anterior horn cells in the spinal cord (i.e., lower motor neurons) and the brain stem nuclei. "Our research provides another example of neurodegenerative diseases caused by mutations in calpain genes and increases the genetic heterogeneity of non-5q SMAs, adding CAPN1 to the list of spinal muscular atrophy causative genes." (PMID 35126465, 2021).
ampullary carcinomas (1 paper, 2012). "The expression of calpain-1, calpain-2 and calpastatin cytoplasmic and nuclear expression was tested to determine associations with clinicopathological criteria in the pancreatic and the grouped bile duct and ampullary cancers." (PMID 23140395, 2012). "In the bile duct and ampullary carcinomas calpain-1 expression had a statistically significant correlation with cytoplasmic calpastatin expression (r = 0.425, P < 0.001) and nuclear calpastatin expression (r = 0.295, P = 0.002), but not with calpain-2 expression." (PMID 23140395, 2012).
aortic aneurysm (1 paper, 2013). A ruptured aneurysm located in the wall of the proximal portion of the descending aorta proceeding from the arch of the aorta. "Calpain-2 compensates for loss of calpain-1, and both calpain isoforms are involved in AngII-induced aortic aneurysm formation in mice." (PMID 23977256, 2013).
autoimmune disease (1 paper, 2023). A disorder resulting from loss of function or tissue destruction of an organ or multiple organs, arising from humoral or cellular immune responses of the individual to their own tissue constituents. "TREML1, CAPN1, and DBN1 seem the most relevant based on their functions in immune responses, cytoskeletal remodeling, cell adhesion/migration and association with chronic inflammatory and autoimmune diseases." (PMID 37205098, 2023).
autosomal recessive spastic paraplegia (1 paper, 2021). "This is exemplified by two individuals with a homozygous nonsense mutation (c.1969G>T, p.(Glu657*)) in CAPN1, compatible with a diagnosis of autosomal recessive spastic paraplegia (SPG76)." (PMID 33726816, 2021).
basal cell skin carcinoma (1 paper, 2022). "For example, expression level of CAPN1 mRNA is significantly higher in basal cell skin carcinoma than in normal tissue, while the protein level of calpain-1 is reduced, probably due to higher proteolytic and autolytic activity." (PMID 39086981, 2022).
breast tumor (1 paper, 2023). "Likewise, calpain-1 and calpain-2 could be considered the proteases of two faces controlling physiological mammary gland homeostasis, but also promoting breast tumor progression." (PMID 37795261, 2023).
Cachexia (1 paper, 2023). Severe weight loss, wasting of muscle, loss of appetite, and general debility related to a chronic disease. "An in vitro cachexia model using liver cancer cells and a C26 colon cancer study demonstrated that Calpain-1 was highly upregulated in these cells, which was opposite to the calpastatin level, and the Ca2 + -dependent proteolytic pathway was highly activated in the C26 cachexia rat model." (PMID 37217930, 2023).
cervical cancer (1 paper, 2025). A primary or metastatic malignant neoplasm involving the cervix. "μ-Calpain CAPN1 cleaves pRB after lysine 810 in human cervical cancer cell lines, suggesting that a Calpain homolog could cleave LIN-35/Rb in the absence of DAF-18/PTEN." (PMID 40199585, 2025).
chronic myeloid leukemia (1 paper, 2017). "However, some studies showed that calpain-1 and calpain-2 play opposite roles in retinal ischemia/reperfusion injury but both, calpain-1 and calpain-2, provide neuroprotection in chronic myeloid leukemia." (PMID 29036897, 2017).
CO poisoning (1 paper, 2017). "Based on these findings, we inferred that NBP treatment could improve the ultrastructure and cognitive function of hippocampus in rats with CO poisoning, which is associated with the down-regulation of both calpain 1 and CaMK II proteins." (PMID 28232802, 2017). "The administration of NBP could balance the expressions of calpain 1 and CaMK II proteins and improve cognitive function through maintaining ultrastructural integrity of hippocampus, and thus may play a neuroprotective role in brain tissue in rats with CO poisoning." (PMID 28232802, 2017).
cognitive decline (1 paper, 2025). "GPX4-knockout mice exhibit cognitive decline and neurodegeneration associated with increased lipid peroxidation and ERK1/2 activation—not calpain 1 (CAPN1)—indicating ferroptosis, not apoptosis, as the driver." (PMID 40761698, 2025).
colon cancer (1 paper, 2020). "HCT116 have increased levels of CAPN2 in comparison with other colon cancer cell lines, and we also confirmed that protein levels of CAPN1 and CAPN2 are significantly higher than those in HeLa or HEK293 cells while the amount of CAST is moderate." (PMID 33078830, 2020). "For this purpose, we compared the expression levels of CAPN1, CAPN2, CAPNS1 and CAST in different cell lines and chose human HCT116 colon cancer cells." (PMID 33078830, 2020).
diabetic cardiomyopathy (1 paper, 2026). Diabetic cardiomyopathy is a disorder of the heart muscle in people with diabetes. "The beneficial effect of calpain-1 gene knockout on diabetic cardiomyopathy was similar to that of AsIV, and calpain-1 knockout did not further enhance the beneficial effect of AsIV." (PMID 41725932, 2026).
Duchenne muscular dystrophy (1 paper, 2016). Duchenne muscular dystrophy (DMD) is a neuromuscular disease characterized by rapidly progressive muscle weakness and wasting due to degeneration of skeletal, smooth and cardiac muscle. "Additionally, both an elevated CAPN1 activity and an increased capacity of exchange by NCX were observed in the mdx model of Duchenne muscular dystrophy, where higher sarcoplasmic Ca2+ levels were found." (PMID 26503425, 2016).
glioma (1 paper, 2018). A benign or malignant brain and spinal cord tumor that arises from glial cells (astrocytes, oligodendrocytes, ependymal cells). "In agreement with the previous data demonstrating that in glioma cells, RT-associated cell death was mainly a mixture of necrosis and autophagy, we show a dose-dependent increase in cathepsin D cleavage and calpain 1 autolysis (necrosis)." (PMID 29486795, 2018).